ALB (albumin)
Diseases named in the same sentence as ALB in open-access papers (continued):
Sharing a sentence is not in itself a finding about the gene and the disease.
anemia (continued). "While this study did not mention if the patients had secondary anemia, they did find that patients with the highest LRG1 tertile also had significantly lower levels of hemoglobin and albumin, similar to the association observed in our study." (PMID 37513518, 2023). "Many altered biochemical parameters such as anaemia, thrombocytopenia, elevated bilirubin, CRP, procalcitonin, AST, ALT, ferritin, GGT, IL 6, and reduced sodium and albumin levels can be related to both malaria and MIS-C therefore require proper interpretation." (PMID 35897103, 2022). "Blood tests revealed no anemia with 11.5 g/dL hemoglobin (Hb) and a slightly reduced albumin level at 3.9 g/dL." (PMID 35928693, 2022). "Further, the evidence thus far at best suggests a prognostic, and not predictive, role of anemia, hypomagnesemia, low albumin, and low vitamin D, in CIPN development." (PMID 35054049, 2022). "Univariate logistic regression analysis showed that FAR (OR = 1.535, 95% CI = 1.361–1.731, P < 0.001); sex; anemia; CHF; levels of hemoglobin, platelets, SCr, D-dimer, fibrinogen, and albumin; eGFR; LVEF; hydration levels; and use of diuretics were risk factors for PC-AKI." (PMID 36568875, 2022). "Measuring AFB1-albumin adducts during all three trimesters can provide an overall picture of AFB1 exposure during the entire pregnancy and would better illustrate the effect of aflatoxins on anemia." (PMID 34822590, 2021). "Regarding clinical characteristics, a log-rank test showed that high β2M, low albumin, ISS stage > 2, and to a lesser extent anemia, high creatinine levels, and older age predicted shorter OS of patients (p = 0.0004, p = 0.003, p = 0.01, p = 0.06, p = 0.08, p = 0.09, respectively)." (PMID 34502204, 2021). "The removal of furancarboxylic acid, an inhibitor of erythropoiesis, by albumin-leaking HD improved anemia irrespective of BUN level." (PMID 34506574, 2021). "Older age, female sex, anemia, low albumin levels, high BUN levels, and no prescription of ACEIs or ARBs were also associated with noncardiovascular death." (PMID 32379331, 2020). "There were 20 patients (69%) showed anemia, 19 (65.5%) with increased erythrocyte sedimentation rate (ESR), 18 (62.1%) with increased C-reactive protein (CRP), 11 (37.9%) with reduced albumin, 10 (34.5%) with abnormal leukocytes and 2 (6.9%) with of thrombocytopenia." (PMID 33208100, 2020). "Additional analyses demonstrated that, as expected, patients who had an early recovery from anemia exhibited significantly higher baseline values for erythrocytes, Hb, hematocrit, neutrophils and albumin than those who did not recover." (PMID 33072136, 2020). "In the present study, the standard parameters for clinical staging of CanL and follow-up of the dogs, such as albumin/globulin ratio, non-regenerative anemia or renal functions, were assessed individually from the beginning to the end of the study." (PMID 32429309, 2020). "Again, small changes over time in the group without anemia at baseline were observed, with increased levels of uric acid and decreased levels of creatinine at D60 and with increase in albumin levels at D180, comparing with baseline." (PMID 33072136, 2020). "GA is superior to HbA1c as a marker for glycemic control because it is not affected by serum albumin, anemia, or ESA usage." (PMID 31498022, 2019). "Other factors, including age, sex, pretreatment platelet count, serum ALB level, and anemia were not significantly correlated with DM in this study, which is consistent with other studies." (PMID 28445271, 2017). "Mean serum albumin concentration was 3.8 ± 0.71 g/dL in patients with anemia and 4.06 ± 0.8 g/dL in patients who did not have anemia (p=0.31)." (PMID 26261697, 2015). "In both studies, mean serum albumin in patients with anemia was lower than in patients without anemia." (PMID 26261697, 2015).
anemia (continued). "The relationship between anemia and inflammatory process in hemodialysis patients as assessed by high serum CRP has been addressed in several studies but the data regarding serum albumin and anemia in hemodialysis patients are scarce." (PMID 26644884, 2015). "Firstly: the key determinants of Zn status, including: hair zinc levels, iron or hemoglobin status for anemia, presence of acute illness, inflammation markers, including C Reactive Protein and serum Albumin were not estimated in this study." (PMID 24401366, 2014). "In our study, anemia (hemoglobin level) and nutritional status (albumin) were also evaluated, and there was difference in mean hemoglobin level, but not in mean albumin level." (PMID 24774860, 2014). "As can be observed, baseline values of proteinuria and serum albumin were significantly different between patients with and without anemia." (PMID 23295149, 2013). "In deeply invasive cases, the absence of overt antenatal anemia or inflammation may lead to relatively high preoperative hemoglobin, albumin, and lymphocyte levels." (PMID 41227180, 2025). "Furthermore, other factors influencing mass balance calculations, like non-bleeding-related anemia, third space losses that were not drained and therefore not sampled, and altered albumin metabolism, were not fully explored." (PMID 40057738, 2025). "The modeling group of MM patients was used, with pulmonary infection occurrence during chemotherapy in MM patients was set as the dependent variable (yes = 1, no = 0), while age, ISS stage, ECOG score, anemia, neutropenia, and albumin levels were set as independent variables." (PMID 41232431, 2025). "The laboratory and biomarkers variables more frequently identified among patients with PTB were prediabetes (46%), anaemia (59%), high neutrophils count (37%), low lymphocytes count (27%), high ferritin level (39%), CRP > 10 mg/L (79%), high alkaline phosphatase (43%), and low albumin level (58%)." (PMID 40028635, 2025). "Additionally, participants with anemia had significantly lower concentrations of serum ferritin and albumin, while their hsCRP levels were significantly higher compared with those for the participants without anemia (all p < 0.05)." (PMID 39408389, 2024). "However, all other tests, including those for anemia-related CBC, inflammation-related CBC, albumin, globulin, lipase, creatine kinase, electrolytes, urine protein, urine creatinine, urine protein creatinine ratio, and urine-specific gravity, showed low (0.3–0.5) to negligible (<0.3) correlations." (PMID 39199847, 2024). "In addition, we also observed that the albumin levels in children with anemia were significantly lower than those in the non-anemia group." (PMID 38886797, 2024). "Nonetheless, it cannot be ruled out that the decreased anemia markers (hemoglobin and albumin) reported in this study might also have contributed to the upregulation of the inflammatory markers, leading to an increase in LRG1 levels." (PMID 37513518, 2023). "Compared with those without anemia, the patients with anemia had higher systolic blood pressure and more severe proteinuria, but lower baseline body mass index, eGFR, HbA1c, and fasting plasma glucose and serum albumin concentrations." (PMID 35188068, 2022). "We also did not evaluate albumin, copper and zinc levels which can rarely contribute to anaemia." (PMID 32875517, 2021). "Moreover, patients with anemia had lower BMI (25.2 ± 4.4 vs. 26.3 ± 4.2 kg/m2), diastolic BP (72 ± 14 vs. 75 ± 13 mmHg), albumin (39.5 ± 5.9 vs. 43.1 ± 4.5 g/L) and triglycerides (1.8 ± 1.9 vs. 1.9 ± 1.3 mmol/L) compared to those without anemia." (PMID 34789178, 2021). "Similarly, in our cohort, most patients were older and accompanying CKD, AMI, anemia and CHF, which may lead to the status of low serum albumin level." (PMID 32867690, 2020).
anemia (continued). "Multiple regression analysis using models 1 and 2 showed that the prevalence of anemia gradually increased in accordance with the progression of G category in each set of criteria, independent of age, A category, albumin level, CRP, and sex (notably, sex was only included for JSDT2 Criteria)." (PMID 32687544, 2020). "In this study, neither anemia nor serum levels of albumin had an impact on mortality." (PMID 33184445, 2020). "Severe frailty was observed in 29.5% of the study group, significantly more frequently in the no-OAC group, and severe frailty and anemia were the independent negative determinants of OAC prescription at discharge when adjusted for albumin level < 35 g/L, HAS-BLED ≥ 3 and CHA2DS2-VASc score." (PMID 31471772, 2020). "Additionally, all of the criteria to classify abnormal biochemistry (increased CRP or IL6, anemia and low serum albumin) were not available." (PMID 31118043, 2019). "However, these factors may not completely account for the relationship between RDW and mortality, because RDW is independently associated with mortality even after adjustment for total cholesterol, albumin, and SOFA score, anemia, transfusion and so on." (PMID 27936006, 2016). "Laboratory findings are often nonspecific but may show evidence of GI malabsorption (e.g., low albumin, calcium, folate, iron, and red blood cell count), elevated erythrocyte sedimentation rate (ESR), elevated platelet counts, anemia, and increased acute phase reactants such as C-reactive protein." (PMID 26240765, 2015). "Our findings suggest that patients with stage IV CRC with low ploidy score and CRP levels, absent or mild anaemia, and normal albumin levels might derive greatest benefit from palliative chemotherapy." (PMID 23840958, 2013). "The neutrophil count, platelet count, albumin, whether or not anemia, NLR, PLR, and the pathological response of locally advanced rectal cancer after NCRT were not statistically significant (P > 0.05), whereas serum CEA level was significantly associated with locally advanced rectal cancer." (PMID 36103002, 2023). "Not like albumin, traditional nutrition screening and assessment tools were not sensitive enough to indicate the existence of anemia in this study, maybe because the items in these two tools contained only phenotype and etiologic parameters but not the items reflecting the internal environment." (PMID 35646973, 2022). "Finally, the ESRD CPM Project focuses on intermediate outcomes of anemia management, vascular access, dialysis adequacy, and serum albumin and does not collect data on the more firm clinical outcomes of neurocognitive development, hospitalization, or mortality." (PMID 18509683, 2009). "Patients with advanced diseases, low levels of albumin and ALI, anemia, and primary focus without any surgical treatment have a higher risk of cancer cachexia." (PMID 35898878, 2022). "The univariate analysis demonstrated that OS was superior in patients with non-sarcopenia, non-alcohol, NRI ≥ 100, albumin ≥ 40 g/L, TATI > 83.0, SATI > 27.8, VATI > 49, non-anemia, cervical and upper-thoracic ESCC, T stage 1–2, N stage 0–1 and TNM stage I–II." (PMID 35501704, 2022). "There were higher levels of WBC, CRP, ALT, and lactate and lower levels of albumin, PLT, and hemoglobin in the non-survivor group (all P < 0.001), indicating more severe inflammation, liver dysfunction, poor circulation, and anemia in the non-survivor group." (PMID 36210933, 2022). "In the present study, it was also observed that the negative correlation between HbA1c and albumin was greater in the presence of several common conditions, including older age (>45 y), higher FPG levels, and anemia." (PMID 34055818, 2021). "Noteworthy, TB patients who were anemic at pre-ATT exhibited increased values of ferritin, ESR, CRP and decreased levels of albumin, AST and ALT at day 60 than those who did not have anemia at the study enrollment." (PMID 30718725, 2019).
anemia (continued). "Heterogeneity observed within the centenarian population regarding TC, albumin, and TIBC might thus be related to nutrition rather than inflammation, liver function, and anemia." (PMID 37726432, 2024). "However, albumin can also reflect many non-nutritional factors that frequently occur among CKD patients, including anemia, infections, urinary and dialysate losses, and hydration status." (PMID 36839171, 2023). "Previous anaemia occurred more frequently in no PAC group and S/P-albumin was lower in PAC group." (PMID 34319998, 2021). "A nephrotic syndrome was diagnosed (serum albumin 2.5 g/dL, proteinuria 9.6 g/24 h), with a rise in serum creatinine (1.17 mg/dL), active urinary sediment (red blood cells (RBC) 27/mm3, white blood cells (WBC) 60/mm3), and non-regenerative anemia (hemoglobin 10.7 g/dL, reticulocytes 35 G/L)." (PMID 32646497, 2020).
COVID-19 (724 papers, 2020 to 2026). A disease caused by infection with severe acute respiratory syndrome coronavirus 2. "Increasing levels of albumin were associated with a decreased COVID-19 risk, whereas bilirubin was positively associated with COVID-19 risk in this study." (PMID 39449666, 2025). "A decreased albumin level, known for its anti-inflammatory and antioxidant properties, has been associated with poor outcomes in severe COVID-19, likely reflecting systemic inflammation and nutritional status." (PMID 40506946, 2025). "Elevated cytokines and kidney injury biomarkers, including NGAL, CysC, and low albumin, are strongly associated with higher mortality in COVID-19 patients." (PMID 40649865, 2025). "Binary logistic regression analysis showed that twenty indicators were independently associated with reduced serum albumin in adult COVID-19 patients." (PMID 41574293, 2025). "Risk factors of severe COVID-19 in patients with IIM were low serum albumin and high ferritin levels." (PMID 39928605, 2025). "Some causal associations were reported in these studies between COVID-19 and over 15 proteins, as well as the markers albumin, bilirubin, MPK-1, MIP1b, and ACE2." (PMID 39449666, 2025). "In COVID-19 survivors, low serum albumin and poor nutritional status have been directly associated with slower improvement in grip strength and persistent fatigue, dyspnea, and exercise intolerance, all of which contribute to a diminished quality of life." (PMID 41439932, 2025). "The decrease in kidney function, characterized by an increase in the level of creatinine, GRF, and urea and a decrease in serum albumin, was associated with a significantly increased risk of in-hospital death in T2D complicated by COVID-19." (PMID 38398069, 2024). "A decreased level of serum albumin among COVID-19 patients is associated with a higher incidence of adverse outcomes and a higher mortality rate." (PMID 39144651, 2024). "The diagnostic sensitivity of albumin levels for predicting mortality in patients with COVID-19 at a cut-off value of 3.7 g/dl was 82.5% (95% CI, 67.2–92.7), and the specificity was 77.4% (95% CI, 72.8–81.5)." (PMID 38639116, 2024). "Our study combined high CRP, high neutrophils, low lymphocytes, and low albumin as a group and defined a population at high risk of death, providing a new predictive strategy for COVID-19." (PMID 38698064, 2024). "CRBSI was significantly associated with SARS-CoV-2 infection, COVID-19-related pneumonia, lower median albumin levels, and shorter catheter dwell times." (PMID 39203438, 2024). "Several biomarkers, including lactate dehydrogenase, albumin, and lactate/albumin (L/A), have been associated with increased mortality in COVID-19 patients." (PMID 38576552, 2024). "Serum albumin levels can serve as a novel and simple early biomarker to identify COVID-19 patients at high risk of death." (PMID 38639116, 2024). "Serum albumin levels showed an inverse association with the severity of COVID-19 at the time of hospitalization, i.e., lower albumin levels were associated with severe and critical disease." (PMID 38515170, 2024). "Biomarkers such as CRP, ferritin, NLR, and albumin were chosen for their strong associations with COVID-19 pathophysiology." (PMID 39767161, 2024). "Recently, Gök and colleagues (2021) evaluated the L/A ratio in patients with COVID-19, reporting its superior diagnostic accuracy for predicting 30-day mortality compared to lactate and albumin alone." (PMID 38576552, 2024). "Older age, low albumin levels, and high globulin levels were also significantly associated with severe COVID-19." (PMID 37823314, 2023). "Specifically, the CRP/albumin ratio (CAR) arose as an independent risk factor for 30-day mortality rate in patients with COVID-19." (PMID 37762957, 2023).